HIF1A (hypoxia inducible factor 1 subunit alpha)
Diseases named in the same sentence as HIF1A in open-access papers (continued):
Sharing a sentence is not in itself a finding about the gene and the disease.
malignant glioma (23 papers, 2007 to 2025). A grade III or grade IV glioma arising from the central nervous system. "This also represents a starting point for the clinical use of compounds inhibiting the activity of HIF-1α to help treat malignant gliomas." (PMID 40429943, 2025). "In further experiments, we knocked out HIF‐1α in the malignant cells to study how the change in the level of HIF‐1α influences the microenvironment of malignant glioma." (PMID 37194413, 2023). "Our experimental results suggested that M2‐like TAMs activated the PI3K/Akt/HIF‐1α/CA9 pathway in the malignant glioma cells via SPP1‐CD44‐mediated intercellular interaction to promote the recurrence of malignant glioma." (PMID 37194413, 2023). "The results showed that the level of HIF‐1α was significantly increased in the tumor tissues of recurrent malignant glioma." (PMID 37194413, 2023). "The results suggested that the increase of the HIF‐1α level in the microenvironment of recurrent malignant glioma was attributed to the malignant cells, TAMs, and endothelial cells." (PMID 37194413, 2023). "The results suggested that carboxyanhydrase 9 (CA9) was the downstream protein of HIF‐1α and was related to the immune microenvironment of malignant glioma." (PMID 37194413, 2023). "Consistent with the immunohistochemical results, the data of the scRNA‐seq analysis also suggested that the level of HIF‐1α in each cell cluster in the microenvironment of recurrent malignant glioma was generally higher than that in primary malignant glioma." (PMID 37194413, 2023). "In order to clarify the exact mechanism of borneol induced apoptosis in malignant glioma, this study further evaluated the effect of Borneol on HIF-1α, mTORC1, eIF4E expression." (PMID 32626528, 2020). "Here we show that STAT6 is epigenetically silenced in some cases of malignant glioma, ultimately preventing cancer cell death by inducing HIF-1α expression via the mTOR-S6K-S6 pathway." (PMID 31530290, 2019). "The transcription factor HIF-1α has emerged as a key regulator of oxygen homeostasis in malignant glioma and its expression correlates with a malignant glioma phenotype in patient samples." (PMID 27764809, 2016). "Overall the data demonstrates that US28 expression in fibroblasts and malignant glioma cells results in an extensive increase of HIF-1α protein levels, whereas gene transcription is unaffected." (PMID 27602585, 2016). "To examine if the ability of HIF-1α to modulate Lon expression is preserved in malignant glioma cells, we transfected both D-54 and U-251 cells with siRNAs (4 different constructs) directed against HIF-1α or a scrambled siRNA control." (PMID 27764809, 2016). "We demonstrate that in malignant glioma cells, Lon is regulated by HIF-1α, it controls survival, and mediates adaption to hypoxia." (PMID 27764809, 2016). "Second, hypoxia typically present in malignant glioma is expected to stimulate accumulation of HIF-1α and subsequent expression of genes involved in glucose metabolism and in the suppression of oxidative phosphorylation." (PMID 24728273, 2014). "In most human cancers including malignant glioma, HIF-1α expression promotes tumor growth, angiogenesis and disease progression." (PMID 21050481, 2010). "Silencing of HIF-1α has been shown to inhibit hypoxia-mediated cell migration and invasion in in vitro and in vivo malignant glioma models." (PMID 21050481, 2010). "Further investigations are necessary to study the normoxic expression of HIF-1α in malignant glioma cell lines." (PMID 21050481, 2010). "In conclusion, our results suggest that inhibition of HIF-1α is a promising strategy to reduce cell survival and to enhance the response of malignant gliomas to radiotherapy." (PMID 21050481, 2010). "HIF-1α antisense treatment suppressed HIF-1α expression by up to 80% under both normoxic and hypoxic conditions and resulted in significant resistance of U87 malignant glioma cells to the cytotoxicity of cisplatin, etoposide, and vincristine." (PMID 17999771, 2007).
malignant glioma (continued). "PI3K/Akt/HIF‐1α/CA9 activation promotes the recurrence of malignant glioma." (PMID 37194413, 2023). "M2-like TAMs were found to increase in recurrent malignant glioma significantly and the M2-like TAMs could activate the PI3K/Akt/HIF-1α/CA9 pathway in the malignant glioma cells via SPP1-CD44-mediated intercellular interaction." (PMID 37612741, 2023). "Furthermore, we used immunohistochemical techniques and proteomics analysis to study the effect of the PI3K/Akt pathway and its downstream factor HIF‐1α on recurrent malignant glioma." (PMID 37194413, 2023). "Moreover, the M2‐like TAMs can activate the PI3K/Akt/HIF‐1α/CA9 pathway in the malignant glioma cells via SPP1‐CD44‐mediated intercellular interaction." (PMID 37194413, 2023). "The HIF‐1α/CA9 pathway provides a new therapeutic target for the treatment of malignant glioma." (PMID 37194413, 2023). "We then compared the HIF‐1α level of each cell type in the primary and recurrent malignant glioma." (PMID 37194413, 2023). "Thus, our study demonstrates that PRMT3 promotes GBM progression by enhancing HIF1A-mediated glycolysis and metabolic rewiring, presenting a point of metabolic vulnerability for therapeutic targeting in malignant gliomas." (PMID 36351894, 2022). "Therefore, the purpose of this study was to investigate the effect of apoptosis induced by borneol in human malignant glioma primary cells, and the effect and relation of borneol on regulation of the mTORC1/eIF4E/HIF-1a signaling pathway." (PMID 32626528, 2020). "In addition, direct knockdown of HIF-1α using siRNA resulted in the abrupt decrease of Lon mRNA expression, confirming that HIF-1α effectively controls Lon expression in malignant glioma lines as was previously shown in normal cell lines." (PMID 27764809, 2016). "In addition, in mice bearing orthotopic malignant gliomas, inhibition with bevacizumab of vascular endothelial growth factor, which is an important stimulus for angiogenesis, increased nuclear HIF-1α and HIF-2α, and expression of WNT11." (PMID 26861754, 2016). "However, the resulting biological effects of IDH mutation and (R)-2HG accumulation remain controversial, exemplified in the case of HIF1A signaling, a major oncogenic pathway in malignant glioma." (PMID 26538165, 2015). "In this study, the effects of 3 to 30 μM BA on cytotoxicity, migration, the protein expression of PARP, survivin and HIF-1α, as well as radiosensitivity under normoxic and hypoxic conditions were analyzed in the human malignant glioma cell lines U251MG and U343MG." (PMID 21906280, 2011). "Results from this in vitro study suggest that inhibition of HIF-1α is a promising strategy to sensitize human malignant gliomas to radiotherapy and that CA9 could serve as an indicator of effective HIF-1-related radiosensitization." (PMID 21050481, 2010). "Results suggest that inhibition of HIF-1α decreased tumor growth in malignant gliomas." (PMID 21050481, 2010). "However, little is known about the impact of HIF-1α inhibition on radioresistance of malignant glioma." (PMID 21050481, 2010). "We already know that HIF-1α regulates the action of vascular endothelial growth factor (VEGF), which is probably the primary mediator of angiogenesis during malignant gliomas." (PMID 40429943, 2025). "In conclusion, we demonstrated that PRMT3, highly enriched in malignant gliomas, is essential for GBM growth in vitro and in vivo at least in part by activating HIF1α and glycolysis signaling." (PMID 36351894, 2022). "In the present study, we analyzed the effects of HIF-1α inhibition by two alternative strategies, siRNA targeting of HIF-1α or CTM, on the radioresistance of two malignant glioma cell lines." (PMID 21050481, 2010). "In the present study, we analyzed the inhibitory effects of two alternative HIF-1 targeting strategies, HIF-1α-siRNA and CTM, on HIF-1α expression and that of its target gene carbonic anhydrase 9 (CA9) in human malignant glioma cells." (PMID 21050481, 2010).
malignant glioma (continued). "Indeed, there is evidence of HIF-1α and glucose transporter 3 (GLUT3) expression and of increased lactate accumulation in malignant gliomas." (PMID 24728273, 2014).
chronic obstructive pulmonary disease (22 papers, 2015 to 2025). A chronic and progressive lung disorder characterized by the loss of elasticity of the bronchial tree and the air sacs, destruction of the air sacs wall, thickening of the bronchial wall, and mucous accumulation in the bronchial tree. "miR-186 has been recently reported to control inflammatory fibroblasts via regulating HIF-1α in chronic obstructive pulmonary disease." (PMID 33536061, 2021). "More recently, miR-186 has been shown to impair the proliferation of inflammatory fibroblasts through regulation of HIF-1α in chronic obstructive pulmonary disease." (PMID 33536061, 2021). "Aberrant activation of hypoxia-inducible factor (HIF)-1α is frequently encountered and promotes oxidative stress and inflammation in chronic obstructive pulmonary disease (COPD)." (PMID 29765317, 2018). "Moreover, chronic obstructive pulmonary disease (COPD) is associated with significantly reduced capillary density, leading to a state of hypoxia, which in turn activates hypoxia-inducible factor (HIF-1α), also important for angiogenesis." (PMID 38473833, 2024). "Hence, CS-induced HIF-1α expression contributes to the pathogenesis of chronic obstructive pulmonary disease (COPD) and therefore can also play a role in the development of BPD." (PMID 28150141, 2017). "In this study, we investigated the effects of estrogen and GPER on HIF-1a and MIF expression, cardiac arrhythmias, and inflammation during hypobaric hypoxia." (PMID 40108505, 2025). "The role of hypoxia‐inducible factor 1 alpha (HIF‐1α) in the development and progression of chronic obstructive pulmonary disease (COPD) has also been demonstrated." (PMID 30575333, 2019). "However, HIF-1α is abundant in chronic obstructive pulmonary disease, which may interact with cytokines through epidermal growth factor receptor (EGFR)/phosphoinositide 3-kinase (PI3K)/protein kinase B (AKT) pathway and further up-regulate HIF-1α self." (PMID 36724056, 2023). "In addition, in large airway specimens obtained from patients with chronic obstructive pulmonary disease (COPD) but not from smokers without COPD, nuclear HIF1α staining was detected in areas of goblet cell hyperplasia." (PMID 33015064, 2020).
steatosis (22 papers, 2014 to 2026). Increased lipid within the cytoplasm of cells. "Furthermore, DEC1-expressing plasmid, as well as the PHD inhibitor dimethyloxaloylglycine (DMOG), was able to ameliorate steatosis in HIF-1α-deficient mice." (PMID 27094811, 2016). "Mice with hepatocyte-specific HIF-1α deletion have shown reduced levels of steatosis as compared to wild-type mice." (PMID 40572736, 2025). "Our results suggest GPS’s anti-inflammatory and anti-steatosis effects in NASH progression are related to the suppression of HIF-1α through the restoration of L-serine and glycine and the activation of PPARα through increased EPA and DHA." (PMID 38515850, 2024). "HIF-1α activation is involved in alcohol-induced liver injury and steatosis, whereas HU induces liver injury by upregulating HIF-1α and inhibiting arginine biosynthesis in mice." (PMID 39872146, 2024). "Hepatocyte-specific HIF-1α expression is a determinant of lipid accumulation and liver injury in alcohol-induced steatosis in mice." (PMID 35907977, 2022). "We next examined effects of loss of hepatic Hif-1α gene on CDD-induced tissue damage, steatosis, and fibrosis in mouse liver." (PMID 30242180, 2018). "The current review focuses on the induction of liver inflammation, fibrosis, and steatosis by free cholesterol via the hypoxia-inducible factor 1α (HIF-1α), a main oxygen-sensing transcription factor involved in all stages of NAFLD." (PMID 29955245, 2018). "Targeted disruption of VHL in the liver increases the expression of HIF-1α and HIF-2α, and hepatic steatosis in vhl-deficient mice is caused by HIF-2α rather than HIF-1α." (PMID 40141255, 2025). "Furthermore, HIF‐1α is not only upregulated in hepatocytes, where it induces steatosis, but also in macrophages of NASH patients." (PMID 35187072, 2021). "Mice with stabilized HIF-1α levels in macrophages showed higher steatosis and liver inflammation." (PMID 35187072, 2021). "Accordingly, the liver might promote steatosis by enhancing HIF-1α and inhibiting SIRT1 signaling that stimulates hepatosteatosis in ob/ob mice, and these phenomena were neutralized by losartan." (PMID 34360607, 2021). "In the PHD2/PHD3 double knockout mice, it is demonstrated that HIF-2α, but not HIF-1α, is associated with steatosis." (PMID 27094811, 2016). "Hepatic Hif1α deletion in a mouse model of NAFLD (mice fed a choline deficient diet), however, led to lower Lipin1 mediated PPARα/PGC1α pathway activation, which worsened steatosis relative to wild type mice, suggesting HIF1α is required to maintain FAO in NAFLD." (PMID 34692739, 2021). "HIF-1α inhibition could be relevant to the resolution of all NAFLD-related clinical parameters (including steatosis, chronic hepatitis, and fibrosis) and HCC, whereas its activation is relevant to the protection against ischemia/reperfusion- (I/R-) related injury and acute hepatitis." (PMID 29955245, 2018). "Finally, the progressive accumulation of fatty acids in the cells would reduce succinate levels, thereby blunting the increase in HIF-1α and LIPIN1 and ultimately aggravating steatosis." (PMID 32912335, 2020). "One study reported that hepatocyte-specific HIF-1α deletion in mice was protective against an ethanol containing Lieber-DeCarli diet, whereas another study with the same animal model and almost identical dietary protocol found that depletion of HIF-1α in hepatocytes aggravated steatosis." (PMID 31083568, 2019). "In particular, constitutive expression of HIF-2α, but not HIF-1α, in hepatocytes enhanced expression of lipogenic genes such as SREBP1c, FASN and promoted lipid storage as well as steatosis." (PMID 31083568, 2019).
Autoimmunity (21 papers, 2012 to 2026). The occurrence of an immune reaction against the organism's own cells or tissues. "It has been noted that activated B cells produce interleukin-10 (IL-10) to inhibit autoimmunity by suppressing pathogenic T cells and HIF-1α deficiency results in an increased B1-like cell population which further causes autoimmunity." (PMID 30413999, 2019). "HIF-1α is important for the development of B cells, with HIF-1α deficiency in chimeric mice leading to autoimmunity." (PMID 23772226, 2013). "Specifically, HIF-1α deficiency has been shown to induce dramatic defects in B lymphocyte development and autoimmunity, and IL-1 and TNF-α have been found to highly trigger HIF-1α expression." (PMID 24710489, 2012). "High numbers of Tfh cells can be associated with autoimmunity and paradoxical decreases in antigen-specific GC B cell responses; restraining Tfh cell numbers, through the activities of PD-1, HIF-1α, and other inhibitory molecules, may be a key quality control." (PMID 35145086, 2022). "In Hif1a/Rag2-deficient chimeric mice display B cell lineage defects including abnormalities in peritoneal B1 cells and high levels of IgG and IgM antibodies directed against dsDNA, a phenotype of autoimmunity." (PMID 33808042, 2021). "Furthermore, smoking leverages the hypoxia induced risk of autoimmunity by inhibiting the HIF-1α inhibitor- HDAC." (PMID 29598831, 2018). "We showed that CXCR1 strengthened the pro-inflammation cytokines production of DCs and further accelerated inflammation and autoimmunity disease progression via a positive feedback loop of CXCL5/CXCR1/HIF-1α." (PMID 37709757, 2023). "The metabolic regulation of the two cell types has some similarities, e.g. the utility of hypoxia induced factor (HIF)1α during low oxygen tension, to prevent autoimmunity and regulate inflammation." (PMID 36311757, 2022). "However, high HIF-1α expression in T cells or Treg cells would likely induce lethal autoimmunity in the host." (PMID 33024109, 2020). "Hence, in an attempt to increase energy production for cell survival, HIF-1α also produces antigenic targets, thereby promoting autoimmunity." (PMID 29598831, 2018). "It has been proven that the absence of HIF-1α in the lymphoid tissues of chimeric mice causes abnormal B cell development and autoimmunity, via the impairment of hypoxia-induced cell cycle arrest in B cells." (PMID 29762526, 2018). "However, Hif1a haploinsufficiency had little impact on the dysregulated IFNγ production in miR-142–deficient Treg cells and failed to prevent development of fatal autoimmunity in Foxp3CremiR-142fl/fl mice." (PMID 35180231, 2022). "Noteworthy, HIF-1α tips the balance between TH17 and Treg differentiation, and indirectly promotes autoimmunity in patients." (PMID 29762526, 2018). "With regard to autoimmunity, markers for T helper 17 (TH17) cells and hypoxia-inducible factor-1 alpha (HIF-1a) could be useful." (PMID 37568452, 2023). "In the present study, we found that a moderate increase of HIF-1α expression in HIF-2α-KO Treg cells did not result in autoimmunity in Cd4CreHif2af/f or Foxp3CreHif2af/f mice." (PMID 33024109, 2020).